GDF15 (growth differentiation factor 15)
Diseases named in the same sentence as GDF15 in open-access papers (continued):
Sharing a sentence is not in itself a finding about the gene and the disease.
cardiovascular disease (continued). "The biomarkers sST2, GDF-15, H-FABP and suPAR showed promising results in multiple cardiovascular diseases." (PMID 40869494, 2025). "Growth differentiation factor 15 (GDF-15) was originally described as a stress-induced cytokine, and a biomarker of aging and cardiovascular diseases." (PMID 38686386, 2024). "Serum factors such as GDF15 and SERPINE1, both biomarkers of cardiovascular disease and highly conserved SASP factors, were increased with HFD and reduced with DPP4i treatment." (PMID 37097759, 2023). "The effects of two metformin targets, AMP-activated protein kinase (AMPK) and growth differentiation factor 15 (GDF15), on cardiovascular diseases have been studied." (PMID 37734206, 2023). "Inhibiting DPP4 activity did not change the abundance of circulating DPP4 in serum, although it did reduce the levels of GDF15, a conserved SASP factor and cardiovascular disease biomarker that increased with HFD." (PMID 37097759, 2023). "There is increasing evidence that markers such as growth differentiation factor 15 (GDF-15) and ST2 can provide useful prognostic implications for subjects with established cardiovascular disease, including both acute and chronic HF." (PMID 36556427, 2022). "GDF-15 and CXCL10 are proatherogenic inflammatory markers, and they are promising biomarkers in cardiovascular diseases in humans, including atherosclerosis." (PMID 36001144, 2022). "Thus, we conclude that while plasma GDF-15 is associated (in unadjusted analyses) with cardiovascular risk factors in renal transplanted children, it is not useful as a biomarker for cardiovascular disease in this group because of the very strong association with renal function." (PMID 32089755, 2020). "The cytokine growth differentiation factor-15 (GDF-15), a member of the TGF beta superfamily, has recently been discovered to play an important role in cardiovascular diseases." (PMID 23800095, 2013). "Mitochondrial fission contributes to the development of cardiovascular disorders by inhibiting GDF-15, which suggests that GDF-15 may have a cardio-protection role." (PMID 39781722, 2025). "Limited data from pediatric studies confirmed the presence of increased plasma/serum GDF15 concentrations in children with CKD without features of cardiovascular disease." (PMID 40076962, 2025). "Of the biomarkers under study, growth/differentiation factor-15 (GDF-15), Galectin-3 (Gal-3), and soluble suppression of tumorigenicity 2 (sST-2) stand out as potential key markers for cardiovascular disease (CVD) and its outcomes, possibly offering insights into the cardiac structure." (PMID 38672149, 2024). "Circulating growth differentiation factor 15 (GDF-15), expressed in liver, kidney, intestine and placenta abundantly, is a biological marker of negative prognosis in cardiovascular disease." (PMID 36864452, 2023). "Growth Differentiation Factor-15 (GDF-15) is a member of the transforming growth factor-β (TGF-β) superfamily, and it is highly expressed in the myocardium and endothelial cells in patients with cardiovascular disease." (PMID 35892913, 2022). "On the other side, the markedly higher prevalence of smokers in the highest tertile of GDF-15 has been reported in a Framingham cohort of subjects without overt cardiovascular disease." (PMID 34217226, 2021). "Levels of GDF-15, CRP and Cystatin C were determined in three repeated measurements collected 5 years apart in the DAN-MONICA (Danish-Multinational MONitoring of trends and determinants in Cardiovascular disease) cohort (participants at baseline n = 3785)." (PMID 29771963, 2018). "Novel biomarkers such as growth differentiation factor 15 (GDF-15), a distant member of the transforming growth factor beta superfamily, have been explored as a relevant gene in kidney injury and as prognostic biomarker in multiple disease entities, including cardiovascular disease." (PMID 37008733, 2023).
cardiovascular disease (continued). "Growth differentiation factor-15 (GDF-15), also known as macrophage inhibitory cytokine-1 or non-steroidal anti-inflammatory drug-activated gene has been identified as a biomarker of treatment response and prognosis in cardiovascular diseases." (PMID 35250619, 2022). "While GDF-15 expression outside the reproductive organs is low to absent, it is upregulated in pathological conditions that involve inflammation and/or oxidative stress, e.g., cancer, cardiovascular disease, pulmonary disease, diabetes and renal disease." (PMID 34829345, 2021). "Growth differentiation factor-15 (GDF-15) has been identified as a strong marker of cardiovascular disease; however, no data are available concerning the role of GDF-15 in the occurrence of organ dysfunction during coronary artery bypass grafting (CABG) associated with cardiopulmonary bypass (CPB)." (PMID 25171167, 2014). "However, it is important to note that GDF-15 is not kidney-specific; its expression may also be influenced by systemic conditions such as cardiovascular disease, malignancies, and chronic inflammatory states." (PMID 40731746, 2025). "The growth differentiation factor-15 (GDF-15) is an inflammaging biomarker, predictor of cardiovascular disease (CVD), and several other non-communicable diseases (NCD) that represent the main causes of death globally, for which prevention is essential." (PMID 40448790, 2025). "Growth differentiation factor 15 (GDF15) is a strong predictor of cardiovascular events and mortality in individuals with or without cardiovascular diseases." (PMID 28806401, 2017). "This study investigated whether circulating levels of GDF‐15, E‐selectin, CD14, and ST2 are predictors of death and cardiovascular outcomes in 981 individuals who did not have a history of cardiovascular disease (CVD) during follow‐up periods of 5, 10, and 20 years." (PMID 40495286, 2025).
metabolic disorders (103 papers, 2015 to 2026). "The TGF-β family member growth differentiation factor-15 (GDF15) is emerging as a diagnostic and therapeutic target for metabolic disorders." (PMID 37745718, 2023). "GDF-15 might also control metabolic homeostasis and is implicated in the pathogenesis of metabolic disorders and neurodegenerative processes." (PMID 40875171, 2025). "Indeed, a recent cross-sectional study on 98 adult patients affected by metabolic disorders reported a positive association between GDF15 circulating levels and serum markers of liver injury (AST, ALT, and GGT) and inflammation (i.e., acute-phase proteins)." (PMID 40650260, 2025). "Thus, assessing the levels of GDF-15 and associated metabolic proteins can be useful in clinical trials targeting aging and metabolic disorders in PLWH on ART." (PMID 38895099, 2024). "To further explore whether GDF15 is associated with metabolic disease in the Vpr mouse models, we measured Gdf15 gene expression in the liver of male mice." (PMID 35510313, 2022). "Not surprisingly, therefore, mitochondrial dysfunction is the hallmark of a wide range of pathologies and metabolic disorders and has been suggested as a common underlying factor responsible for the induction of GDF15 in these highly variable pathophysiologic contexts." (PMID 34831213, 2021). "Furthermore, whether GDF15 serves a causal role in metabolic diseases or simply reflects energetic stress remains controversial." (PMID 35510313, 2022). "Future longitudinal and interventional studies are warranted to validate these findings and further elucidate the potential role of GDF-15 in metabolic disease progression." (PMID 40722664, 2025). "Here, we analyzed the circulating levels of GDF15 in patients with metabolic disorders to explore their potential relationship with baseline MASLD and the incidence of CV disease after a 10-year follow-up." (PMID 40076667, 2025). "This ability of GDF-15 to bridge cardiovascular, renal, and metabolic disorders makes it an essential focus for both diagnosis and prognosis in CKM, offering insights into disease severity and progression." (PMID 39781722, 2025). "These future studies are essential to fully establish the clinical utility of GDF-15, paving the way for its potential applications in the realm of metabolic disorders." (PMID 40722664, 2025). "Administration of murine mature GDF15 have been proven to show therapeutic effects against metabolic disorders." (PMID 40673270, 2025). "In this review, we aim to provide a comprehensive overview of the emerging understanding of GDF15 in cardiovascular and metabolic diseases, highlighting its mechanistic and biological regulation, clinical implications, and therapeutic potential." (PMID 40837873, 2025). "The diverse roles of GDF15 in both cardiovascular and metabolic diseases underscore its therapeutic potential." (PMID 40837873, 2025). "GDF-15 has a role in various physiological and pathological processes, encompassing its involvement in metabolic disorders, cardiac dysfunction, and renal disorders." (PMID 39781722, 2025). "Growth differentiation factor 15 (GDF15) as a stress response cytokine is involved in the development and progression of several diseases associated with metabolic disorders." (PMID 38725041, 2024). "Growth differentiation factor 15 (GDF15) is a stress-response cytokine related to a wide variety of metabolic diseases." (PMID 39596055, 2024). "Because GDF-15 is deemed a marker of cellular aging and mitochondrial stress, and PLWH exhibit premature aging and metabolic disorders, we measured plasma levels of GDF-15 in PLWH (including IRs and INRs) and healthy subjects (HS) by ELISA." (PMID 38895099, 2024). "These insights enhance our understanding of GDF15’s functions in adipose tissue physiology and underscore its potential as a therapeutic target for metabolic disorders." (PMID 39505926, 2024).
metabolic disorders (continued). "Evidence shows that GDF-15 is a prognostic biomarker of metabolic disorders related to adiposity and obesity." (PMID 39420932, 2024). "Among metabolic disorders, it is notable that elevated plasma GDF-15 levels have previously been found in T2DM patients." (PMID 39456699, 2024). "The expression of GDF-15 is increased in cardiovascular diseases and metabolic disorders, probably as part of a counterregulatory process intended to reestablish homeostasis." (PMID 39420932, 2024). "In contrast genetic deletion of Gdf15 results in an increase in food intake AT mass and consequent metabolic disorders, such as adiposity." (PMID 36992609, 2023). "GDF15 can suppress food intake and inflammation and thus is a potential candidate to treat many metabolic diseases." (PMID 35853851, 2022). "We sought to compare plasma GDF15 levels in PLWH and HIV‐negative persons and mouse models expressing the HIV accessory protein Vpr (that recapitulate HIV‐associated metabolic disorders) and determine their relationship to metabolic parameters." (PMID 35510313, 2022). "Higher levels of GDF15 in a spectrum of inflammatory and metabolic diseases formed the prediction that PLWH harbor elevated levels of GDF15 in plasma." (PMID 35510313, 2022). "As patients with severe vascular and metabolic diseases were excluded from the study, increased GDF-15 levels are probably due to the different age between the two groups (mean difference 7 years)." (PMID 34572118, 2021). "Growth differentiation factor-15 (GDF-15), a transforming growth factor-β superfamily member, has broad target specificity and exerts diverse biological effects through multiple signaling pathways, drawing attention to its role in metabolic diseases." (PMID 42063769, 2026). "NAG-1/GDF15 has gained attention as a pleiotropic biomarker for several metabolic disorders." (PMID 40316530, 2025). "In addition, GDF15 also plays a role in metabolic adaptation to systemic inflammation and is causally associated with T2DM, making it a therapeutic target for metabolic diseases." (PMID 40119457, 2025). "Finally, as drugs targeting the GDF-15 pathway are already under development for metabolic diseases, our results directly inform and potentially accelerate their repurposing for the treatment of NAFLD." (PMID 41333917, 2025). "In our study, 11 of the 12 patients (91.5%) with high plasma GDF-15 levels had a BMI above 25 kg/m2, which may also support the conclusion that these patients have a more severe metabolic disorder." (PMID 39456699, 2024). "Elevated levels of GDF-15 and the presence of mitochondrial DNA deletions may be a consequence of carbohydrate metabolism disorders in patients and thus a predictor of the process of accelerated aging." (PMID 39456699, 2024). "Since PLWH exhibit metabolic disorders, we measured the plasma levels of 92 metabolic proteins using the Olink proteomic assay (metabolic panel) and then correlated changes in their levels with the circulating GDF-15 protein in the same subjects." (PMID 38895099, 2024). "Recent studies have found that GDF-15 regulates lipid and carbohydrate metabolism, reduces food intake and body mass, and improves insulin sensitivity, suggesting its potential therapeutic applications in metabolic diseases." (PMID 37152921, 2023). "The increased focus on GDF15 in recent years is likely a reflection of the growing recognition of its potential as a therapeutic target for diseases involving mitochondrial dysfunction, such as neurodegenerative and metabolic disorders." (PMID 37035249, 2023). "Therefore, identification of important SNPs of this molecule and their role in the MetS would improve the current knowledge of the effect of GDF15 in metabolic disorder." (PMID 36992609, 2023). "It is not known if GDF-15 is elevated due to cellular stress in those with poor physical function, mitochondrial dysfunction, or bystander marker for other underlying metabolic disorders." (PMID 37152099, 2023).
metabolic disorders (continued). "Better understanding of the roles of endogenous FGF21 and GDF15 in health and disease might lead to the development of new therapies to treat metabolic disorders." (PMID 37818094, 2023). "Collectively, these findings suggest that GDF15 may be a promising therapeutic target for the regulation of both energy metabolism and the AT immune microenvironment in metabolic diseases." (PMID 35909571, 2022). "It has been reported that GDF15 plays an important role in some metabolic diseases." (PMID 34669736, 2021). "Furthermore, targeting GDF15 can improve body weight and improve multiple metabolic diseases in mice models." (PMID 35083256, 2021). "GDF15 and FGF21 are endocrine factors associated with liver and metabolic diseases." (PMID 32179785, 2020). "Through complementary human and animal experiments supported by the reanalysis of large‐scale human transcript datasets, we demonstrate that GDF15 is required for the prevention of aging‐induced development of metabolic diseases by regulating tissue and systemic inflammation." (PMID 32691494, 2020). "However, further study is required to establish a functional role for GDF15 in aging‐mediated inflammation and metabolic diseases in humans." (PMID 32691494, 2020). "Since both FFAs and GDF-15 concentrations increase in metabolic diseases, FFAs may represent potential activators of GDF15 expression." (PMID 33302552, 2020). "Besides using GDF-15 as a biomarker, GDF-15 polypeptide itself is patented to treat or ameliorate metabolic disorders." (PMID 26273671, 2015). "Therefore, serum GDF15 may be a serum marker for metabolic disorders in patients with T2DM combined with MS." (PMID 41497484, 2025). "Considering the association of GDF-15 with inflammatory and metabolic diseases, the aim of this study was to explore the hypothesis that GDF-15 may be linked to PCOS and its related complications, which commonly include inflammation and metabolic disorders." (PMID 39420932, 2024). "However, these outcomes have fueled the development of GDF15 agonists against metabolic disease." (PMID 38762719, 2024). "The ample evidence above indicates that lung infection and inflammation may lead to the onset of AE and upregulation of GDF-15 in IPF subjects, which can further cause metabolic disorders of lipid and protein and coagulation dysfunction and then aggravate the conditions of these patients." (PMID 35784345, 2022). "Therefore, GDF-15 may have a relationship with the development of several metabolic disorders, which could be a potential target of T2D." (PMID 36187475, 2022). "Thus, even if GDF15 increases with age, it may be difficult to regulate tissue inflammation and to prevent metabolic disorders in humans and mice." (PMID 32691494, 2020). "Therefore, reduced levels of GDF15 and γ-GT imply the attenuation of existing mitochondrial and oxidative stresses by HBOT, which suggest therapeutic potential for metabolic diseases or neurodegenerative diseases associated with oxidative stress and mitochondrial dysfunction." (PMID 33120884, 2020). "Previous research has demonstrated that GDF-15 affects metabolism and insulin sensitivity by activating GFRAL, suggesting its involvement in metabolic disorders, oxidative stress responses, and inflammation." (PMID 41019919, 2025). "Growth differentiation factor 15 (GDF15) and fibroblast growth factor 21 (FGF21) are stress-induced cytokines increased in age-related and metabolic disorders." (PMID 40828431, 2025). "The study provides valuable insights into the posttranscriptional regulation of GDF15 by CNOT6L and highlights the potential of targeting this pathway for the treatment of metabolic disorders." (PMID 40837873, 2025). "Additionally, GDF15 has a protective effect against genetic and diet-related obesity.GDF15 overexpression improves insulin sensitivity, and its knockdown enhances blood glucose levels in diabetic rat models, supporting its beneficial effect on metabolic diseases." (PMID 35634503, 2022).